IL22 (interleukin 22)
Diseases named in the same sentence as IL22 in open-access papers (continued):
Sharing a sentence is not in itself a finding about the gene and the disease.
tumor (continued). "Whereas T cell-specific deletion of Il1ra reduced IL-17A/IL-22-dependent tumorigenesis, Il1ra ablation in neutrophils impaired their function in bacterial control, leading to microbial tumor invasion, which elicited exacerbated inflammation and CRC." (PMID 35517498, 2022). "Pro-inflammatory mediators such as IL-22, IL-6, IL-2, and IL-17 play a key part in maintaining tumor microenvironment, promoting immunosuppression, angiogenesis, and coordinating the interactions between immune cells." (PMID 36249057, 2022). "Based on the pleiotropic role of IL-22 it is important to identify the mechanisms of IL-22 regulation especially in the tumor microenvironment." (PMID 35295139, 2021). "Numerous studies suggested the clinical significance of Th-17 responses in contributing to poor survival outcome in HCC patients by the pro-tumor functions of IL-17, IL-21 and IL-22, including tumor proliferation and angiogenesis." (PMID 33805946, 2021). "IL-22 regulates a globally altered gene expression profile in tumor cells, including signaling pathways, cell proliferation, and migration." (PMID 34941188, 2021). "Infiltrating Th17 cells then secrete IL-17 and IL-22 to promote primary tumor resistance to combination therapy." (PMID 33972557, 2021). "Studies published so far, mainly based on murine models, support a tumor promoting role of IL-22 in hepatocellular carcinoma and liposarcoma." (PMID 34296212, 2021). "IL22 is upregulated in tumor tissues and serum from patients with recurrent NSCLC compared to primary NSCLC tumors and is associated with poor clinical outcome." (PMID 34944848, 2021). "When IL-22 is released by immune cells, it can act on cancer cells to promote tumor growth, aggressiveness, and treatment resistance 28-30." (PMID 33390778, 2021). "IL-1α and IL-1β in the tumor microenvironment play critical roles in colorectal cancer growth by inducing tumor-elicited inflammation through IL-17A and IL-22 production in T cells." (PMID 33406733, 2021). "NK cells can both produce IFN-γ and exert cytolytic activity against tumor cells, while ILC3s are regulatory cells, which produce IL-22." (PMID 33467134, 2021). "But the expression of IL-22 and IL-22R1 had weak correlation with patient gender (P = .662, P > .99), age (P = .153, P = .565), tumor location (P = .374, P > .99), T stage (P = .204, P = .140), and pathologic differentiation (P = .061, P = .626)." (PMID 34941188, 2021). "IL-17 and IL-22 cytokines have been directly implicated in BCC and SCC progression and tumor growth in mouse xenografts, as well as progression, cell migration, and local invasion in BCC cancer cell lines." (PMID 33972406, 2021). "In a xenograft model of RCC using the A498 cell line, IL-22, a cytokine secreted by Th22 cells, slowed the tumor growth." (PMID 34931665, 2021). "These γδ T cells then produced IL-17 to promote neutrophil infiltration and inflammation in the tumor microenvironment; they also expressed IL-22, amphiregulin, and other effector molecules to directly enhance tumor cell proliferation." (PMID 34108973, 2021). "Gene therapy designed to drive expression of IL-22BP, a secreted binding protein that inhibits IL-22 signaling, reduces tumor burden in mice." (PMID 34489941, 2021). "IL-22 is a cytokine with tumor-promoting properties, which can mediate the attraction of immunosuppressive immune cells and regulate the release of pro- and anti-inflammatory cytokines." (PMID 34422810, 2021). "Further research is required to elucidate the mechanism of IL-22 effecting directly and indirectly on tumor cells in LSCC." (PMID 34941188, 2021). "IL-22 has been reported to both increase and decrease formation of tumors depending on tissue and model system but a tumor-promoting effect is more commonly observed." (PMID 33692792, 2021). "Given the roles of Th17 and Th22 cells in promoting tumor development, IL-17A, IL-17F, and IL-22 are also promising targets in CRC." (PMID 34489941, 2021).
tumor (continued). "Both reports found either an increased tumor burden in IL-22TG mice or a decreased amount of tumors in IL-22-deficient mice, corroborating the HCC-promoting effect of IL-22." (PMID 33851257, 2021). "As tumor stage and grade progressed, the frequencies of Th22 and Th17 cells and the level of plasma IL-22 significantly increased." (PMID 33390778, 2021). "The results of a previous study revealed that cancer cells induce interleukin-22 (IL-22) production from T cells CD4 memory via interleukin-1 (IL-1) to promote tumor growth." (PMID 33390791, 2021). "In many tumor environments, IL-22 signaling affects both the proliferation and stemness of healthy epithelium and dysplastic epithelium, providing a possible explanation for its diverse effects." (PMID 33851257, 2021). "Percent of IL-22-positive T-cell in small intestine and lymph node were higher than that in tumor tissue (p < 0.05)." (PMID 32649314, 2020). "IL-22 plays a particularly important role in immune cell–tumor interactions, as it is solely secreted by immune cells and exerts its effects only on non-hematopoietic cells." (PMID 32069807, 2020). "The deletion of IL‐22 gene leads to the arrest of malignant transition stage, and reduced invasion and tumor burden." (PMID 31725949, 2020). "We observed elevated IL22 expression and IL-22+ cells in the peritumoral tissue compared to tumor tissue." (PMID 32100077, 2020). "IL-22 is produced by innate lymphoid cells, IL-17+ and IL-22+ cells and is involved in both wound healing and tumor development." (PMID 32298379, 2020). "In further support of this, the aberrant expression of the IL-22 cognate receptor, interleukin-22 receptor 1 (IL-22R1), has been observed in many types of tumor, including lymphomas and pancreatic, lung, and colon cancers." (PMID 31935914, 2020). "We also showed that IL‐22 levels substantially increased in the TME during the invasion stage of tumor progression." (PMID 31725949, 2020). "In colorectal tissue, IL-22 is a significant tumour-promoting cytokine influencing tumorigenesis, stemness, anti-apoptosis and cell proliferation." (PMID 32760201, 2020). "Short term IL-22 production protects against genotoxic stress, whereas uncontrolled IL-22 activity promotes tumor growth; therefore, tight regulation of IL-22 is essential." (PMID 32451418, 2020). "Results showed a significant decrease (P < 0.01) in the expression of all transcription factors in tumor cells purified from IL‐22−/−/PyMT mice compared to controls." (PMID 31725949, 2020). "Because IL-1β and IL-23 are upstream cytokines in regulating production of IL-22, we tested the impact of IL-1β and IL-23 on tumor growth." (PMID 32649314, 2020). "IL-22 BP is a natural factor for attenuating IL-22 effects in tumour angiogenesis and anti-apoptosis, which showing a prospective potential for CRC treatment." (PMID 32760201, 2020). "We evaluated the plasma concentrations of Th1 (IL-2, IFN-γ, and TNF-α), Th2 (IL-4, IL-5, IL-6, and IL-10), Th9 (IL-9), and Th17 (IL-17A, IL-17F, IL-21, and IL-22) cytokines in tumor-bearing mice by flow cytometry." (PMID 32802733, 2020). "In the diethylnitrosamine-induced HCC model, tumor formation was significantly reduced in IL-22 knockout mice." (PMID 32760208, 2020). "Polarization of Th17 and related cytokines including 1L-17A, IL-17F, IL-21, IL-22, TNF-α, and IL-6, in CRCs is associated with tumour promoting inflammation, immunosuppression, induction of pro-angiogenic factors, and poor patient outcome." (PMID 32635383, 2020). "Our results are in line with these findings as the inactivation of IL‐22 gene reduces both the number of tumor lesions and the overall tumor burden in IL‐22−/−PyMT mice." (PMID 31725949, 2020). "IL22 treatment significantly promoted the tumor growth in CM models; however, sh-miR-181 treatment notably suppressed the effects of IL22 on CM mice." (PMID 32201538, 2020).
tumor (continued). "Our data showed that IL‐22 is present in the TME from the earliest stages of tumor development, but its expression specifically increased during the early carcinoma/malignant transition stage of tumor progression, suggesting its role in cancer invasion." (PMID 31725949, 2020). "The highest MUC1 expression was achieved 72 hours after IL22 cytokine addition, all the cytotoxic experiments were performed at the 72nd hour to detect the apoptosis of tumor cells." (PMID 31800160, 2020). "In another study it was found that IL-22—whose expression by T cells was increased in TNBC tumor tissues compared to para-tumor and normal areas—induced paclitaxel resistance in TNBC cell lines, accompanied by elevated JAK/STAT3 activation." (PMID 33585241, 2020). "IL-17+ and IL-22+ which are involved in both wound healing and tumor development through activation of STAT3." (PMID 32100077, 2020). "Further characterization of these cells showed that the increased IL-22 frequency in the tumor was owing to an enrichment of IL-17A+IL-22+ double producing CD4+ T cells, whereas IL-17A-L-22+ single producing T cells were not changed." (PMID 32451418, 2020). "Neutrophils can exert tumor-promoting activity by secreting a variety of inflammatory mediators, including vascular endothelial growth factor, interleukin (IL)-6, IL-10, and IL-22." (PMID 32528232, 2020). "The activation of NF‐κB leads to cytokine production, especially IL‐6, IL‐11 and IL‐22, providing an inflammatory environment for the growth of premalignant tumours." (PMID 32347623, 2020). "Protein expression analysis showed the presence of IL‐22 in TMEs during the initiation and hyperplasia stages (4–6 weeks) of tumor development." (PMID 31725949, 2020). "Given that EACs are also usually accompanied by chronic inflammation, we aimed to further characterize the role of IL-22 and IL-17 in this type of tumor." (PMID 32100077, 2020). "Tumor size was also increased by giving both IL-1β and IL-23, an effect reversed by concurrent use of an IL-22 neutralization antibody." (PMID 32649314, 2020). "Interleukin‐22 is upregulated in various human cancers, and multiple studies have shown the tumor‐supporting role of IL‐22 in the growth of these cancers." (PMID 31725949, 2020). "Both mRNA and protein levels of MMP‐3 were found downregulated in tumor cells from IL‐22−/−/PyMT mice compared to control mice." (PMID 31725949, 2020). "Targeting IL-22 activation in CCSC-induced CC with IL-22 antibody dramatically reduced primarily tumour volume, delayed tumour development and increased mouse survival." (PMID 32760201, 2020). "Tumor cells of early‐carcinoma‐stage (10 weeks) primary tumors were purified from IL‐22+/+ or IL‐22−/−/PyMT mice, and mRNA from these cells was used for gene expression analysis." (PMID 31725949, 2020). "For the first time, this study provides an insight into the tumor stage‐specific function of IL‐22 in breast tumorigenesis." (PMID 31725949, 2020). "Multiple studies have shown that inhibition of IL‐22 activity can hamper cancer cell proliferation and tumor growth." (PMID 31725949, 2020). "In murine models, boosted levels of IL-22 reveal an indispensable role of this cytokine in the enhancement of tumor burden and decline in survival rate." (PMID 33042126, 2020). "Giving IL-1β and/or IL-23 increased cell proliferation in 4T1 tumor, which was reversed by concurrent use of an IL-22 neutralization antibody." (PMID 32649314, 2020). "To investigate the inhibition in the tumor growth in IL‐22−/−/PyMT mice, we performed histopathological examinations of mammary glands from 4‐ to 14‐week‐old mice." (PMID 31725949, 2020). "IL-22 is also a controversial cytokine in tumor development; the IL-22-STAT3 axis induces anti-apoptotic genes and provides survival and proliferation signals for both normal and malignant cells." (PMID 32670290, 2020).
tumor (continued). "The arrest of tumor progression at the malignant transition stage in IL‐22−/−PyMT mice suggests its role in invasion and migration." (PMID 31725949, 2020). "Conversely, sustained IL-22-dependent epithelial proliferation leads to tumor progression and neutralizing IL-22 reduced CRC development." (PMID 32010138, 2019). "DCs dampen inflammation initially in UVB-damaged murine skin through phagocytosis of apoptotic keratinocytes, but they subsequently promote tumor progression in an IL-22- and TGFβ1-dependent manner." (PMID 31022866, 2019). "TH17 cells, on the other hand, produce IL-17A, IL-17F, IL-21, and IL-22, which promote tumor growth by favoring antimicrobial tissue inflammation." (PMID 31906017, 2019). "In the absence of IL-22 responses in transformed ApcMin/Min cells, one likely explanation for the tumour-promoting effect of IL-22 in ApcMin/+ mice is provided by our discovery that IL-22 induces expression of iNOS and Duox1/2." (PMID 31770366, 2019). "T cell specific ablation of IL-1R1 similarly decreased tumor-elicited inflammation dependent on IL-17 and IL-22, thereby reducing CRC progression." (PMID 31231372, 2019). "Whereas, IL-10 and IL-22 promote tumor cell survival, proliferation and angiogenesis via signal transducer and activator of transcription (STAT) 1,3,5 signalling pathways." (PMID 31340751, 2019). "Knockout mice of IL-22 binding protein, a soluble receptor for IL-22, display IL-22-dependent tumor growth." (PMID 30894857, 2019). "The increased levels of the IL-22 producing (Th22) cells were also observed in normal, paratumor, and tumor tissues from patients with TNBC, which confirmed the importance of IL-22/JAK/STAT3/MAPKs/AKT in metastasis of this disease." (PMID 31088482, 2019). "Tumor growth inhibition (TGI %) for the gefitinib plus IL-22 group (102.9%) was less than the gefitinib group (120.2%; P value = 0.012)." (PMID 31750252, 2019). "The IL-1 receptor antagonist Anakinra abrogates IL-22 production and reduces tumor growth in a murine breast cancer model." (PMID 31231372, 2019). "IL-22-induced changes in the tumor microenvironment complicate EGFR-TKI acquired resistance, posing challenges for the clinical application of molecular targeted therapies." (PMID 31750252, 2019). "Knockdown of IL-10RA in ALCL cell lines resulted in growth arrest, implicating aberrantly expressed IL-10 and IL-22 in autocrine loops that provided a mechanism for aberrant TYK2 activation in tumor cells." (PMID 30131584, 2019). "ILC3s are the main producers of IL-22, which generally has a tumor-promoting effect, but its condition-dependent nature has been proposed with different roles observed in different cancer microenvironments." (PMID 31781671, 2019). "In a mouse model of HCC, metformin has been shown to reduce tumor growth and to inhibit the IL-22 signaling pathway." (PMID 29892294, 2018). "Previous studies revealed that IL-22 directly targetted IL-22 receptor-expressing cells, enhancing proliferation, promoting tumor growth, serving antiapoptotic effects on lung tumor cells." (PMID 30473538, 2018). "Notch signaling inhibition reduced the IL-22 production by CD4+ T cells from tumor site, and this process was accompanied by down-regulation of AhR mRNA expression, but not RORγt." (PMID 30473538, 2018). "IL-22 stimulation significantly increased tumor cell invasion, which presented as elevated cell numbers passing through the membrane in response to IL-22 treatment (74.50 ± 25.35 compared with 46.01 ± 11.19, P=0.030)." (PMID 30473538, 2018). "IL-22 produced by T cells and NK cells participates in tumorigenesis and tumor progression, and mediates chemoresistance, which is enhanced in colon of 5-Fu induced mice." (PMID 29124041, 2017). "Histological analyses revealed reduced proliferation in tumor sections, as demonstrated by the upregulation of three genes involved in apoptosis (caspase 7, 9, and Bik) and cytokine IL-22." (PMID 29209314, 2017).
tumor (continued). "These IL-22-producing cells can promote tumor growth and metastasis by activating STAT3 and inducing the expression of antiapoptotic factors such as BCL-XL." (PMID 28852270, 2017). "Here, Bcl-2 was just regarded as an indicator of cell survival, which partly accounts for IL-22-induced tumor growth." (PMID 28445985, 2017). "In vivo, our data demonstrated that interleukin-22 significantly promoted tumor growth along with elevated expression of c-Myc and hexokinase-2 in mice." (PMID 28445985, 2017). "In murine models of colon cancer, knock-out of the IL-22BP resulted in accelerated tumor growth, which was IL-22 dependent." (PMID 29118756, 2017). "We suppose that in both healthy and tumor contexts, this effect depends on the impaired phosphorylation of molecules involved in the IL-22 proximal signaling, such as IL-22R1 and Tyk2." (PMID 28445952, 2017). "In this study, we focused on IL-22 signaling and identified SOCS3 protein, an intracellular inhibitor of cytokine-associated signaling, as a valid candidate to suppress tumor responses of BCC and SCC." (PMID 28445952, 2017). "A tumor-promoting function of IL-22 via STAT3 stimulation has already been identified in cancers such as hepatocellular carcinoma and lung cancer." (PMID 28492497, 2017). "Numerous studies have shown IL-22 promotes tumor progression through up-regulating Bcl-2 protein expression." (PMID 28445985, 2017). "Although ILCs have been shown to promote tumor growth in mice through IL-22, data in humans indicate CCR6+ TH17 cells to be the major source." (PMID 29118756, 2017). "It has been demonstrated that cell survival-associated Bcl-XL and Bcl-2, proliferation-associated CyclinD1, and VEGF are involved in the promotion effect of IL-22 on tumor." (PMID 28445985, 2017). "Immunohistochemistry of tumor tissues revealed that tumors administrated with IL-22 had higher p-STAT3, c-Myc, and HK2 expression than that in control group." (PMID 28445985, 2017). "Glucose consumption and lactate production were measured in culture supernatants of DLD-1, HT29 and primary tumor cell stimulated with either recombinant IL-22 or PBS." (PMID 28445985, 2017). "The reduction of tumor growth due to KIR-ESS treatment was even more evident when IL-22 was injected in tumor boundaries, with a final volume of 1.5 ± 0.16 cm3 for KIR-ESS group, and 4.3 ± 0.16 cm3 for vehicle or 3.9 ± 0.16 cm3for Ctrl1 group (p < 0.01)." (PMID 28445952, 2017). "The role of IL-22 in color cancer, however, is complex and not only limited to inducing tumor development, as some studies have shown that IL-22 can display antitumor effects." (PMID 27882334, 2016). "In the lung IL-22 has been shown to be expressed by T cells, natural killer-cells, macrophages, epithelial and potentially also by tumour cells." (PMID 27388918, 2016). "The mechanisms how IL-22 confers stemness in tumor cells compared with other pro-tumorigenic cytokines also signaling through STAT3, such as IL-6 and IL-11, warrant further investigation." (PMID 27148488, 2016). "Blocking of IL-17 merely reduced inflammation, while blocking of IL-22 led to a significant decrease in tumor burden." (PMID 28536374, 2016). "Subcutaneous injection of primary CRC cells together with anti-IL-22 antibody treatment strongly inhibited tumor development and growth." (PMID 27148488, 2016). "In the absence of carcinogens or bacterial infection, transgene expression of IL-23 activated IL-23R+ILC, which responded by producing IL-17, IFN-γ, and IL-22 which contributed to tumor development." (PMID 27882334, 2016). "Amongst the complex cytokine network involved in tumor progression, we suggest that immunocompetent cells can interact with tumor cells and secrete IL-22 to promote GBM tumor development." (PMID 25793261, 2015). "In liver, gastric or breast cells, IL-22 enhances tumor growth and progression by activating STAT3, followed by ERK1/2 and/or Akt phosphorylation." (PMID 25793261, 2015).